U3 (Small nucleolar RNA U3 )
Synonyms: LOC124901220
Gene: Small nucleolar RNA gene on chromosome 5 (35,429,064 to 35,429,277, forward strand). Ensembl gene ENSG00000201368.
Gene Ontology:
Biological process: RNA processing
Cellular component: nucleolus
Homologues: Orthologues: chimpanzee U3 (99% identical), macaque U3 (94% identical), dog U3 (71% identical), dog U3 (70% identical), guinea pig U3 (69% identical). Paralogues in human: SNORD3P1 (84% identical), U3 (83% identical), SNORD3G (81% identical), SNORD3E (81% identical), U3 (81% identical), U3 (79% identical), U3 (78% identical), SNORD3H (78% identical), U3 (77% identical), U3 (76% identical), SNORD3D (76% identical), U3 (75% identical), and 12 more.